MTND5P11 (MT-ND5 pseudogene 11)
Gene: Processed pseudogene on chromosome 5 (134,924,648 to 134,926,459, reverse strand). Ensembl gene ENSG00000248923.
Diseases named in the same sentence as MTND5P11 in open-access papers:
MTND5P11 is named in the same sentence as 1 disease in open-access papers, as found by Europe PMC text mining. Sharing a sentence is not in itself a finding about the gene and the disease. The quoted sentences say what the papers report.
calcification (1 paper, 2025). Process by which organic tissue becomes hardened by the physiologic deposit of calcium salts. "By contrast, the mitochondrial-related genes MTND5P11 (log2FC −4.788), MTND4P12 (log2FC −3.897) and MTND4LP30 (log2FC −3.774) were downregulated in individuals with coronary calcifications." (PMID 40703140, 2025).